PIKFYVE (phosphoinositide kinase, FYVE-type zinc finger containing)
Diseases named in the same sentence as PIKFYVE in open-access papers (continued):
Sharing a sentence is not in itself a finding about the gene and the disease.
prion disease (2 papers, 2021 to 2023). A transmissible disease that is caused by a protein that is able to induce abnormal folding of normal cellular proteins, leading to characteristic spongiform brain changes, which are associated with neuronal loss without an inflammatory response. "A protracted unfolded protein response (UPR), typical of prion diseases, also induced PIKfyve deacylation and degradation." (PMID 34291577, 2021). "The phosphoinositide kinase PIKfyve is identified as the driver of brain vacuolation (spongiosis) in prion diseases." (PMID 34291577, 2021). "In the current study, we show that chronic ER stress and PIKfyve depletion link prion infections to the spongiform changes typical of prion diseases." (PMID 34291577, 2021). "Thus, PIKfyve emerges as a central mediator of vacuolation and neurotoxicity in prion diseases." (PMID 34291577, 2021). "While VAC14 and FIG4 levels were not affected at any time point during the progression of prion disease, co‐immunoprecipitation experiments revealed that VAC14 lost its association with FIG4 and PIKfyve in prion‐infected brains at the terminal stage of the disease." (PMID 34291577, 2021). "The relative expression of PIKfyve mRNA splice variants was similar between RML‐infected and control mouse brains, and exploration of a splice alteration database during the progression of prion disease did not identify any differential expression of PIKfyve isoforms." (PMID 34291577, 2021).
calcification (1 paper, 2020). Process by which organic tissue becomes hardened by the physiologic deposit of calcium salts. "The production of TNFα in microglia could be affected by miR32-5p targeting PIKfyve, and these results will be beneficial to reveal the mechanism of brain arterial calcification." (PMID 31952480, 2020).
cardiomyopathy (1 paper, 2017). A disease of the heart muscle or myocardium proper. "Our study reveals the importance of PIKfyve inhibition in the treatment of cardiomyopathy in obese mice and propose new therapeutic avenue to improve cardiometabolic phenotype in obese patients." (PMID 28396567, 2017).
colorectal adenocarcinoma (1 paper, 2023). The most common type of colorectal carcinoma. "It is suggested that the combination of the PIKfyve inhibitor and p38MAPK is best suited for colorectal adenocarcinoma." (PMID 37189432, 2023).
conjunctivitis (1 paper, 2022). Inflammation of the conjunctiva of the eye. "In addition, it was observed that PIKfyve inhibitor-treated mice developed what appeared to be conjunctivitis one day prior to succumbing to disease, which was absent in vehicle-treated animals that died or in uninfected, treated control." (PMID 35962188, 2022).
developmental delays (1 paper, 2016). "Loss of function mutations in a downstream effector of PIKfyve, the TRP channel TRPML-1 (also known as mucolipin-1) leads to mucolipidosis type IV, entailing developmental delays, psychomotor abnormalities, intellectual disability and a shortened lifespan." (PMID 26934981, 2016).
hepatocellular carcinoma (1 paper, 2024). A malignant tumor that arises from hepatocytes. "Inhibition of PIKfyve induces lysosome-associated cytoplasmic vacuolation in hepatocellular carcinoma cells." (PMID 38891085, 2024).
influenza (1 paper, 2024). An acute viral infection of the respiratory tract, occurring in isolated cases, in epidemics, or in pandemics; it is caused by serologically different strains of viruses (influenzaviruses) designated A, B, and C, has a 3-day incubation period, and usually lasts for 3 to 10 days. "Intrinsically, PIKFYVE is found to be involved in influenza and RSV infections, and its inhibitors are promising for a pan-viral approach against respiratory viruses." (PMID 38674024, 2024).
keratoconus (1 paper, 2023). A degenerative, structural disorder of the eye, characterized by a cone-shaped protrusion of the cornea. "Although LOXL2 has previously been linked to keratoconus and may enhance the development of the disease, the clinical and genetic associations seem to suggest that it is especially the PIKFYVE gene that contributes to the development of the disease." (PMID 37895187, 2023).
multiple myeloma (1 paper, 2021). "PIKfyve inhibitors disrupted lysosomal function, autophagic flux, and the high basal necessity of autophagy in plasma cells and multiple myeloma cells." (PMID 33597819, 2021). "Therefore, inhibition of PIKfyve was suggested as a novel target for multiple myeloma." (PMID 33597819, 2021).
Myocardial fibrosis (1 paper, 2021). "In this context, we show that pharmacological inhibition of PIKfyve by Apilimod limits myocardial fibrosis development upon injury, culminating in the preservation of organ function." (PMID 33995670, 2021). "Additionally, we observed a reduction in myocardial fibrosis following chronic PIKfyve inhibition, suggesting a potential role of PIKfyve in cardiac fibroblasts reprogramming." (PMID 33995670, 2021).
nonsmall cell lung cancer (1 paper, 2021). "The aim of the present study was to investigate the effects of phosphatidylinositol-3-phosphate 5-kinase (PIKfyve) inhibitor, YM201636, on nonsmall cell lung cancer (NSCLC) cells growth, tumorigenicity, and claudin (CLDN) expressions." (PMID 33597819, 2021).
Salmonella Infections (1 paper, 2017). Infections with bacteria of the genus SALMONELLA. "In ASFV infection, PIKfyve could exert a similar function as observed in the case of Salmonella infection, which also strongly relies on the LE." (PMID 28587154, 2017).
scrapie (1 paper, 2021). A fatal disease of the nervous system in sheep and goats, characterized by pruritus, debility, and locomotor incoordination. "PIKfyve is highly expressed in neurons, yet the neuronal proteins NeuN and synaptophysin were unaffected, suggesting that its loss did not reflect the neuronal loss in scrapie‐sick mice." (PMID 34291577, 2021).
Ventricular hypertrophy (1 paper, 2017). Enlargement of the cardiac ventricular muscle tissue with increase in the width of the wall of the ventricle and loss of elasticity. "Taken together, these results indicate that PIKfyve inhibition reduces cardiac hypertrophy through mitochondrial SIRT3 activation." (PMID 28396567, 2017). "Moreover, chronic PIKfyve inhibition reduces ventricular hypertrophy and improves cardiac function in morbidly obese mice." (PMID 28396567, 2017).
cancer (26 papers, 2016 to 2026). A tumor composed of atypical neoplastic, often pleomorphic cells that invade other tissues. "Cox regression analysis further revealed that high pre-treatment PIKFYVE expression was associated with poorer clinical outcome (P = 0.01) independently of age, sex, race, and cancer type." (PMID 38011559, 2023). "Together, these data nominate DCs as an immune cell in which PIKFYVE may play a significant role in cancer immunity and ICB-associated outcomes." (PMID 38464258, 2024). "Using pre-treatment RNA-sequencing data from tumors obtained from a stage IV ICB-treated pan-cancer cohort (n = 108) at the University of Michigan (U-M), we found that high pre-treatment PIKFYVE expression was significantly associated with poorer response to ICB." (PMID 38011559, 2023). "PIKfyve was also proposed to be implicated in oncogenesis and cancer cell migration." (PMID 30445978, 2018). "Given emerging PIKfyve inhibitors in cancer therapy, our results raise important safety considerations for clinical radiotherapy and position PIKfyve as a potential target for radiation toxicity mitigation." (PMID 42198560, 2026). "The difference in the sensitivity of cancer cells and normal cells to PIKFYVE inhibitors ranges from 300- to 2000-fold." (PMID 38994949, 2024). "Most autophagy-dependent cancers are PIKFYVE-dependent, and their dependency can be related to a intracellular deficiency in PIP5K1C protein." (PMID 38994949, 2024). "Although PIKFYVE inhibitors can be used as a single agent against cancers, combining a PIKFYVE inhibitor with another anti-cancer therapy amplifies its therapeutic potential." (PMID 38994949, 2024). "The danger in elevated levels of PIKFYVE inhibitors resides in the inhibition of secondary targets (Section 6) that will affect normal cells as well as cancer cells." (PMID 38994949, 2024). "Given the range metabolic effects resulting from inhibition of PIKFYVE, selectively terminating autophagy-dependent cancers is only one therapeutic target for PIKFYVE inhibitors." (PMID 38994949, 2024). "Though PIKfyve inhibitors have shown anti-tumor effects in various preclinical cancer models, it is unclear if the activity of DCs directly contributes to its therapeutic effect." (PMID 38464258, 2024). "In an attempt to use PIKFYVE inhibitors as therapeutic molecules, several studies examined the role of PIKFYVE on innate and systemic immunity, and more recently on its role in cancer immunity." (PMID 38994949, 2024). "The sensitivity of autophagy-dependent cancer cells to PIKFYVE inhibitors results from a requirement to synthesize the phosphoinositides required for lysosome homeostasis and autophagy." (PMID 38994949, 2024). "This is particularly true, since p38 MAPK pathways are reportedly activated by PIKfyve inhibitors in cancer cells." (PMID 38253602, 2024). "The conclusion that cancer cells are significantly more sensitive to PIKFYVE inhibitors than normal cells has been confirmed in patient-derived cancer cells (ex vivo) and xenograft tumors derived from cancer cells (in vivo)." (PMID 38994949, 2024). "Collectively, genetic or pharmacologic inhibition of PIKfyve upregulates antigen presentation and enhances cancer cell killing mediated by CD8+ T cells." (PMID 38011559, 2023). "Our current study advances the understanding of how PIKfyve mediates immune evasion in cancer, whereby PIKfyve downregulates surface MHC-I, a complex which is crucial for CD8+ T cell recognition and CD8+ T cell–dependent immunotherapies." (PMID 38011559, 2023). "As expected, we found that genetic or pharmacologic inhibition of PIKfyve resulted in upregulation of antigen presentation in the cancer cells." (PMID 38011559, 2023). "Here, we found that genetic depletion or pharmacologic inhibition of PIKfyve upregulated MHC-I surface expression in cancer cells derived from various lineages." (PMID 38011559, 2023). "The phosphoinositide kinase PIKfyve has emerged as anew potentialtherapeutic target in various cancers." (PMID 37605297, 2023).
cancer (continued). "Although PIKFYVE phosphoinositide kinase inhibitors can selectively eliminate PIKFYVE-dependent human cancer cells in vitro and in vivo, the basis for this selectivity has remained elusive." (PMID 36803256, 2023). "Knockout of PIKfyve in cancer cells led to weakening mTORC1 and retarded tumor growth regardless of the TAMs phenotype." (PMID 37884533, 2023). "PIKfyve is also being considered as a potential target against autophagy-dependent cancers and new molecules have been identified in vitro for this purpose, namely, the WX8 series of potent inhibitors." (PMID 34977038, 2021). "Among those, apilimod appears to be the most promising and is currently in clinical trials as an anti-cancer drug yet its potential as a PIKfyve inhibitor remains only partially characterized." (PMID 30240452, 2018). "One way in which cancer cells might become dependent on PIKFYVE phosphoinositide kinase activity is through oncogenic mutations." (PMID 38994949, 2024). "However, the efficacy of PIKFYVE inhibitors against PIKFYVE-dependent cancers will also be determined by the inhibitor’s secondary targets." (PMID 38994949, 2024). "Given the fact that PIKFYVE is essential for the activities of endosomes, lysosomes and autophagy, it is not surprising that some PIKFYVE inhibitors are more effective than others for a particular cancer." (PMID 38994949, 2024). "Thus, we generated translational insight into the potential of PIKfyve inhibitors for enhancing DC-dependent therapies in cancer, such as ICB and vaccines." (PMID 38942798, 2024). "Thus, inhibitors of PIKFYVE inhibit autophagy and prevent the growth of cancer cells both in vitro and in vivo." (PMID 38414326, 2024). "A second way in which cancer cells might become dependent on PIKFYVE activity is from limited PIKFYVE expression." (PMID 38994949, 2024). "Thus, PIKfyve negatively controls DCs, and PIKfyve inhibition has promise for cancer immunotherapy and vaccine treatment strategies." (PMID 38464258, 2024). "Thus, autophagy-dependent cancer cells that are deficient in their ability to produce PIP2 via conversion of PI4P into PIP2, must depend on PIKFYVE and PIP4K2 isozymes for biosynthesis of PIP2 and PIP3." (PMID 38994949, 2024). "Thus, PIKfyve negatively regulates the function of CD11c+ cells, and PIKfyve inhibition has promise for cancer immunotherapy and vaccine treatment strategies." (PMID 38942798, 2024). "Given that PIKfyve suppresses DC function, we reason that PIKfyve inhibitors may be selected to treat cancers with high PIKfyve expression in tumors and DCs, thereby effectively targeting both tumors and the immune system." (PMID 38464258, 2024). "Of the kinase inhibitor gene targets evaluated, high pre-treatment PIKFYVE, KDR, NTRK1, IKBKB, FLT1, or FGFR1 expression was each associated with lower odds of achieving CR when controlling for cancer type, biopsy site, age at the time of treatment initiation, and ICB agent." (PMID 38464258, 2024). "Given the emerging role of autophagy dysregulation in various diseases, including cancer and neurodegenerative disorders, understanding the interplay between PIKfyve and autophagy pathways may offer novel opportunities for therapeutic intervention." (PMID 38891085, 2024). "In proof-of-principle experiments, we found that PIKfyve inhibition could potentiate the anti-tumor effect of Poly I:C, a cancer vaccine adjuvant." (PMID 38942798, 2024). "Nanomolar concentrations of PIKFYVE inhibitors in groups A, B and C rapidly and reversibly inhibit proliferation of PIKFYVE-dependent cancer cells and pluripotent stem cells concomitant with inhibition of lysosome fission, endosomal trafficking, endosome maturation, and cathepsin maturation." (PMID 38994949, 2024). "Thus, we generated key translational insight into the potential of PIKfyve inhibitors for enhancing DC-dependent therapies in cancer, such as ICB and vaccines." (PMID 38464258, 2024).
cancer (continued). "Consequently, WX8 selectively terminates PIKFYVE-dependent cancer cells by virtue of its ability to selectively inhibit both PIKFYVE and PIP4K2C." (PMID 36803256, 2023). "While PIKfyve inhibition elevated MHC-I surface expression in wild-type cells, it did not further increase surface expression of MHC-I in the Atg5-null or Atg7-null cancer cells, confirming that PIKfyve inhibition upregulated MHC-I surface expression by impairing autophagy." (PMID 38011559, 2023). "Taken together, these results demonstrated that a PIP5K1C deficiency is what distinguishes WX8-sensitive, PIKFYVE-dependent, cancer cells from WX8-resistant non-malignant cells." (PMID 36803256, 2023). "We next determined whether PIKfyve inhibition could enhance efficacy of other types of immunotherapies by first employing the OVA-expressing cancer cells." (PMID 38011559, 2023). "Collectively, our findings suggest that targeting PIKfyve may enhance CD8+ T cell–dependent immunotherapies via elevating surface expression of MHC-I in cancer cells." (PMID 38011559, 2023). "Thus, the ability of PIKFYVE inhibitors to selectively terminate autophagy-dependent cancer cells andretard the growth of tumors derived from them suggests that they have therapeutic potential." (PMID 36803256, 2023). "Successful application of PIKFYVE inhibitors will require a comprehensive understanding of the pathways regulated by these inhibitors, their secondary targets, and the ability to identify PIP5K1C phosphoinositide kinase deficient cancers." (PMID 36803256, 2023). "PIKFYVE inhibitors also disrupt autophagic flux by preventing heterotypic fusion of lysosomes with autophagosomes, thereby exhibiting therapeutic potential against cancers that depend on autophagy for viability." (PMID 36803256, 2023). "It is conceivable that inhibiting the utilization of scavenged protein, for example, by blocking the cytosolic export of amino acids that require PIKfyve activity, could enhance the anti-cancer effects of mTOR inhibition." (PMID 30967004, 2019). "Consequently, several PIKfyve inhibitors have been found to exhibit anti-proliferative capacity and cytotoxicity, bringing to light a potential new modality in anti-cancer therapy." (PMID 30240452, 2018). "Accordingly, PIKfyve inhibitors are now in clinical trials as anti-cancer drugs." (PMID 30240452, 2018). "Therefore, clinically PIKFYVE-dependent cancers could be identified by comparing the ratio of PIP5K1C to PIKFYVE protein in a cancer biopsy with a biopsy from normal tissue." (PMID 38994949, 2024). "Of the 33 patient derived cancers for which RNA levels have been quantified, 14 of them have significantly less PIP5K1C RNA than their paired normal tissues, suggesting that a significant fraction of cancers will respond to treatment with PIKFYVE inhibitors due to a deficiency of PIP5K1C protein." (PMID 38994949, 2024). "To evaluate whether the action of PIKfyve inhibitors was on-target, we treated Pikfyve-wild-type or Pikfyve-null cancer cells with apilimod or ESK981 and found that upregulation of MHC-I surface expression by PIKfyve inhibition was only observed in the wild-type cells but not Pikfyve-null cells." (PMID 38011559, 2023). "We suppose this may because PIKfyve plays different roles in different cancers." (PMID 30445978, 2018). "PIKFYVE and PIP5K1A are enzymes targeted as therapies for cancer, as their inhibition has been shown to induce autophagy, further suggesting our compounds as inducers of autophagy, as both compounds led to an increase in beclin-1 levels." (PMID 39009412, 2024). "At least two PIKfyve inhibitors, apilimod and ESK981 (formerly CEP-11981), are in clinical development for cancer therapy (34, –36)." (PMID 38011559, 2023). "Here, we found that genetic depletion or pharmacologic inhibition of PIKfyve upregulated surface expression of MHC-I in cancer cells, leading to enhanced antigen presentation and improved CD8+ T cell–mediated cancer cell killing in vitro." (PMID 38011559, 2023).